CD14 (CD14 molecule)
Diseases named in the same sentence as CD14 in open-access papers (continued):
Sharing a sentence is not in itself a finding about the gene and the disease.
monocytic leukemia (8 papers, 2012 to 2025). "A human monocytic leukemia cell line THP-1 was differentiated to CD14-positive macrophage-like cells by stimulation with PMA (phorbol 12-myristate 13-acetate) but not M1 or M2 types." (PMID 34071980, 2021). "Numerous studies have identified and adopted THP-1 (human monocytic leukemia cell line) in vitro modeling CD14+ monocytes or CD34+ HPCs that readily differentiate into iDCs and mDCs." (PMID 22808111, 2012). "Oligomannose glycans have been reported as the major N-glycan type in the undifferentiated human monocytic leukemia cell line THP-1, primary blood-derived CD14 + monocytes, and in Caco-2 cells." (PMID 40210651, 2025). "Oligomannose glycans have been reported as the major N-glycan type in the undifferentiated human monocytic leukemia cell line THP-1, primary blood-derived CD14 + monocytes, and in Caco-2 cells 40–43." (PMID 39606433, 2024). "As MM6 represents a monocytic leukemia subtype, we treated MM6 and MM6KO cells with 3 nM phorbol 12-myristate 13-acetate (PMA) and evaluated expression of CD14." (PMID 33659038, 2021). "Using CD14+ peripheral human monocytes and the THP-1 monocytic leukemia-derived cell line, we confirm that sTLR2 generation increases upon treatment with pro-inflammatory agents and requires a post-translational mechanism." (PMID 25531754, 2014).
Pleural effusion (8 papers, 2012 to 2021). The presence of an excessive amount of fluid in the pleural cavity. "Interestingly, indicators of plasma leakage (pleural effusion index and nadir albumin levels) showed statistically significant associations only with viral RNA levels in plasma and CD14+ cells." (PMID 23284680, 2012). "To that, CD14+ macrophages from TB pleural effusion samples were loaded with gamma-irradiated Mtb, extensively washed and co-cultured with autologous CD8+ T cells in the presence or absence of anti-PD-L1 blocking antibodies." (PMID 30655556, 2019). "Although the levels of viral RNA in plasma correlated significantly with RNA levels in CD14+ cell fraction (r2 = 0.474, P = .001), multivariate analysis showed that these parameters independently correlated with pleural effusion index (P = .001)." (PMID 23284680, 2012). "In this context, we aimed to assess the expression of PD-1 pathway receptors on peripheral blood mononuclear cells (PBMC) and TB pleural effusion CD8+T cells and CD14+ cells." (PMID 30655556, 2019). "First, we demonstrate that DC-SIGN expression is present both in CD68+ macrophages found in tuberculous pulmonary lesions of non-human primates, and in the CD14+ cell population isolated from pleural effusions obtained from TB patients (TB-PE)." (PMID 29946317, 2018). "So we detected surface CD163 expression on CD14+ macrophages derived from pleural effusion and peripheral blood in cancer patients or non-cancer patients by flow cytometry, respectively." (PMID 25871392, 2015). "Remarkably, using concentrations of TGF-β similar to those found at inflammatory sites such as pleural effusions, synovial fluid, and tumor-derived ascites (~0.25 ng/ml), we found that all concentrations of PGE2 assessed markedly suppressed the expression of CD1a, preserving CD14 expression." (PMID 29988364, 2018). "InfDCs represented approximately 1% of the total light-density cells in the pleural effusion and were characterized by the expression of CD206, CD14, CD11b, and CD1α, which were absent on blood DCs." (PMID 32052078, 2020). "The levels of viral RNA in plasma and CD14+ cells on fever day-2, but not in CD2+ or CD20+ cells, correlated with the size of pleural effusions, an indicator of the severity of plasma leakage." (PMID 23284680, 2012).
Salmonella Infections (8 papers, 2014 to 2025). Infections with bacteria of the genus SALMONELLA. "Moreover, the DEGs identified here were also involved in other infectious diseases, including pathogenic Escherichia coli infection pathway and Salmonella infection pathway, in both of which the CD14 gene plays a significant role." (PMID 27098998, 2016). "Moreover, in the “Infectious Diseases” pathways, the CD14 gene was significantly enriched in both the pathogenic Escherichia coli infection pathway and the Salmonella infection pathway." (PMID 27098998, 2016). "KEGG analysis of CD14+ monocytes identified several upregulated pathways, such as endocytosis, Salmonella infection, and protein processing in the endoplasmic reticulum." (PMID 40370447, 2025). "The up-regulation of CD14 in porcine alveolar macrophages following stimulation with LPS or Salmonella infection was also reported earlier." (PMID 25270530, 2014). "In the MLN, expression of CD14, TLR2, and MyD88 all increased in response to Salmonella-infection, except in piglets previously innoculated with the probiotic E. coli." (PMID 31847111, 2019). "The Salmonella infection upregulated LBP, CD14, TLR4, and LBP in the colon." (PMID 38003758, 2023).
septic shock (8 papers, 2011 to 2024). Shock caused by infection; frequently caused by gram negative bacteria, although some cases have been caused by other bacteria, viruses, fungi, and protozoa; characterized by fever, chills, tachycardia, tachypnea, and hypotension. "In this study, we found a relationship between CD14 rs2569190 polymorphism and mortality in European septic shock patients who underwent major surgery." (PMID 29426837, 2018). "Firstly, in septic shock, it is believed that CD14+ cells binding with LPS play a role, particularly as septic shock patients often show higher microbial levels." (PMID 38892107, 2024). "CD14+ monocytes of septic shock patients were purified and incubated with either lipopolysaccharide, anti-PD-L1 antibody, isotype antibody, or a combination of lipopolysaccharide and anti-PD-L1 antibody or isotype antibody." (PMID 21349174, 2011). "PD-L1 expression on the classical monocytes (CD14 + + CD16 −) was significantly upregulated among septic shock patients and the 28-day death group than non-septic shock group and 28-day survival group (P < 0.05)." (PMID 37776443, 2024). "Therefore, the effects of dexmedetomidine on CD42a + /CD14 + and HLADR + /CD14 + levels, as well as the inflammatory cytokines TNF-α, IL-6 and IL-10, in septic shock patients were evaluated in the current study." (PMID 37665397, 2023).
systemic sclerosis (8 papers, 2012 to 2026). A chronic disorder, possibly autoimmune, marked by excessive production of collagen which results in hardening and thickening of body tissues. "In blood, expression of surface SIGLEC-1 is restricted to CD14+ monocytes, and has been previously reported to be increased in several other autoimmune diseases, including rheumatoid arthritis, systemic sclerosis (SSc) and primary biliary cirrhosis." (PMID 30053827, 2018).
type 1 diabetes (8 papers, 2014 to 2026). "Singh and colleagues also reported that youths with type 1 diabetes excreted higher amounts of lumican, CD14, and various lysosomal proteins such as ASAH1, CTSD, and NAGA compared to their non-diabetic siblings." (PMID 32453760, 2020). "In the current study, we aimed to investigate possible associations between gut related inflammatory biomarkers including LBP, CD14, TLR4, I-FABP and IL-18 and the presence of CAD and with established CHD, in patients with long-term type 1 diabetes compared to a control group." (PMID 39563343, 2024). "Increased urinary excretion of CD14 (P = 0.0057), HEXA (P < 0.0001), and lumican (P = 0.0014) was replicated in a second cohort of youths with and without type 1 diabetes." (PMID 32453760, 2020).
acute coronary syndrome (7 papers, 2014 to 2026). Signs and symptoms related to acute ischemia of the myocardium secondary to coronary artery disease. "Intermediate monocytes (CD14++CD16+), a highly pro-inflammatory subset, are linked to endothelial activation, thrombus formation, and poor outcomes in acute coronary syndrome (ACS), suggesting a role in the transition to plaque vulnerability." (PMID 41977457, 2026). "(C) Linear regression analysis between circulating levels of CD14+HLA-DRneg/low monocytes and maximum CK (CKmax) in patients with acute coronary syndrome." (PMID 34289931, 2021). "Other study found that CD14++CD16+ monocyte expansion also corresponded with disease progression in other diseases, including HIV infection, and in acute coronary syndrome." (PMID 25392926, 2014). "Our results demonstrate reduced classical monocyte (CD14++CD16-) frequencies in all PWH groups, including PWHART and PWHEC compared to PWOHHIV-, consistent with previous reports from Asian cohorts of PWH and individuals with acute coronary syndrome." (PMID 40936922, 2025).
biliary atresia (7 papers, 2010 to 2025). A rare, biliary tract disease characterized by progressive obliterative cholangiopathy of the intra- and extrahepatic bile ducts, occurring in the embryonic/ perinatal period, leading to severe and persistent neonatal jaundice and acholic stool. "We found a higher frequency of both CD8+ Trm and CD14+CD16+ proinflammatory monocytes in advanced biliary atresia compared to the control group." (PMID 40607400, 2025). "CD14 expression in the liver tissue was reported in biliary atresia (BA) patients and in rats that received surgery for bile duct ligation in order to generate a BA animal model." (PMID 23308276, 2013). "Our previous investigation revealed a significant increase in plasma endotoxin and CD14 levels during biliary atresia." (PMID 22511970, 2012). "We therefore propose that hepatocytes contribute to both the basal systemic levels of sCD14 by contributing to the upregulation of CD14 that occurs during biliary atresia." (PMID 22511970, 2012). "They considered that exposure to portal-derived LPS might lead to CD14 overexpression in biliary atresia." (PMID 34630385, 2021). "We therefore propose that LPS may stimulate CD14 production in liver cells during the early stage of biliary atresia, promoting endotoxin removal, and that endotoxin signaling likely induces liver injury and impairs CD14 synthesis during the later stages." (PMID 22511970, 2012). "Importantly, we showed both CD14+CD16+ monocytes and Kupffer cells to be increased in biliary atresia." (PMID 40607400, 2025).
chronic myelomonocytic leukemia (7 papers, 2018 to 2024). A myelodysplastic/myeloproliferative neoplasm which is characterized by persistent monocytosis, absence of a Philadelphia chromosome and BCR/ABL fusion gene, fewer than 20 percent blasts in the bone marrow and blood, myelodysplasia, and absence of PDGFRA or PDGFRB rearrangement. "The results indicated that a CD14++CD16− "classical monocyte" increase was associated with disease activity, thus suggesting that ECD is similar to chronic myelomonocytic leukemia (CMML)." (PMID 35687294, 2022). "Chronic myelomonocytic leukemia (CMML) is a rare blood cancer of older adults (3 in every 1,000,000 persons) characterized by an increase in clonal CD14+ CD16– classical monocytes and their precursors in the blood and bone marrow." (PMID 39298477, 2024). "Flow cytometric analysis revealed elevated ratio of CD14+CD16+ atypical monocytes, which excluded the possibility of chronic myelomonocytic leukemia." (PMID 35361277, 2022). "Recently, the number of PB monocyte subsets according to CD14 and CD16 expression was shown to be a key biomarker for the diagnosis of chronic myelomonocytic leukemia (CMML)." (PMID 35885563, 2022). "An increase in the CD14++CD16− classical monocyte fraction ≥ 94% of the total monocytes was proposed to rapidly and efficiently distinguish chronic myelomonocytic leukemia from reactive monocytosis." (PMID 30429467, 2018). "CD14 and CD16 expression defines three distinct monocyte sub-populations (classical monocytes CD14+CD16-, intermediate CD14+CD16+ and atypical CD14weakCD16+), whose relative percentages can be disturbed in dysplasia, chronic myelomonocytic leukemia (CMML) and in reactive/inflammatory conditions." (PMID 39544295, 2024).
juvenile idiopathic arthritis (7 papers, 2012 to 2025). Juvenile idiopathic arthritis (JIA) is the term used to describe a group of inflammatory articular disorders of unknown cause that begin before the age of 16 and last over 6 weeks. "To explore the transcriptional landscape of monocytes in oligoarticular juvenile idiopathic arthritis (oJIA), we performed RNA sequencing on CD14+ monocytes isolated from the synovial fluid of oJIA patients and compared them to peripheral blood monocytes from healthy controls." (PMID 41009809, 2025). "An investigation showed that CD14++CD16− and CD14+CD16+ monocyte subsets are activated in systemic juvenile idiopathic arthritis." (PMID 39070795, 2024).
Kawasaki disease (7 papers, 2011 to 2025). A rare inflammatory disease characterized by an acute febrile, systemic, self-limiting, medium-vessel vasculitis primarily affecting children. "On the one hand, IL-35 suppressed CD14+ monocytes induced naïve CD4+ T cell activation in Kawasaki disease in a direct cell-to-cell contact manner." (PMID 32276581, 2020). "CD14+ monocytes, which were purified from eighteen patients with Kawasaki disease, were stimulated with recombinant human IL-35 and lipopolysaccharide (LPS) for 24 h." (PMID 32276581, 2020). "On the other hand, IL-35 dampened TNF-α and granzyme B production by CD14+ monocytes in Kawasaki disease, however, only granzyme B contributed to the cytotoxicity of CD14+ monocytes." (PMID 32276581, 2020). "IL-35 also inhibited tumor necrosis factor-α and granzyme B secretion by CD14+ monocytes from patients with Kawasaki disease, however, only granzyme B was responsible for the cytotoxicity of CD14+ monocytes." (PMID 32276581, 2020). "IL-35 suppressed CD14+ monocytes induced naïve CD4+ T cell activation in Kawasaki disease, and this process required direct cell-to-cell contact." (PMID 32276581, 2020). "Elevated circulating IL-35 played an important immunosuppressive role to CD14+ monocytes function in Kawasaki disease, including direct cell-to-cell contact-mediated naïve CD4+ T cells activation/differentiation and granzyme B-induced cytolytic function." (PMID 32276581, 2020). "The current data indicated an immunosuppressive activity of IL-35 to peripheral CD14+ monocytes in Kawasaki disease." (PMID 32276581, 2020). "The current data further suggested that the increased expression of IL-35 revealed the protective activity in Kawasaki disease probably via suppression the cytotoxicity of CD14+ monocytes." (PMID 32276581, 2020). "We showed an elevation of plasma IL-35 concentration in patients with Kawasaki disease, however, IL-35 receptor in CD14+ monocytes was comparable between Kawasaki disease patients and controls." (PMID 32276581, 2020). "CD14+ monocytes from Kawasaki disease patients induced elevated target HUVECs death in both direct contact (19.45 ± 3.90% vs 15.15 ± 3.87%; Tukey test, p = 0.026) and indirect contact (22.50 ± 7.69% vs 16.58 ± 3.77%; Tukey test, p = 0.033) co-culture systems." (PMID 32276581, 2020). "Furthermore, increased plasmatic levels of IL-35 induce CD14+ monocytes with suppressor activity in Kawasaki disease." (PMID 37445745, 2023). "In consistent with these previous reports, we found that CD14+ monocytes from patients with Kawasaki disease only effectively promoted the activation and differentiation of naïve CD4+ T cells into IFN-γ-producing Th1 and IL-17A-producing Th17 cells under direct contact condition." (PMID 32276581, 2020). "IL-35 played an important immunosuppressive role to CD14+ monocytes function in Kawasaki disease." (PMID 32276581, 2020). "Moreover, CD14+ monocytes from Kawasaki disease were stimulated with recombinant human IL-35 and LPS for 24 h." (PMID 32276581, 2020). "Thus, we hypothesized that IL-35 modulated circulating CD14+ monocytes activity, which contributed to the immunopathogenesis in Kawasaki disease." (PMID 32276581, 2020). "The elevated plasma levels of pro-inflammatory cytokines in Kawasaki disease are accompanied by elevated levels of anti-inflammatory cytokine IL35, which suppresses the ability of CD14+ monocytes to activate naive CD4+ T cells and has a protective effect." (PMID 36104441, 2022). "CD14+ monocytes revealed elevated cytolytic activity in Kawasaki disease, and this process did not require direct cell-to-cell contact." (PMID 32276581, 2020). "IL-35 also dampened CD14+ monocytes-induced naïve CD4+ T cells activation in Kawasaki disease, indicating that elevated IL-35 might play a protective role to suppress extensive adaptive immune response in Kawasaki disease." (PMID 32276581, 2020).
metastatic disease (7 papers, 2012 to 2026). "Drugs were well tolerated and the treatment significantly decreased tumor‐infiltrating CD14+ monocytes, which are associated with tumor progression and metastatic disease, and reduced markers of epithelial‐to‐mesenchymal transition (EMT), reducing the pro‐metastatic capacity of the malignant tissue." (PMID 34184420, 2021). "However, we lack the defined thresholds for CD14 or neutrophil expression due to the limited availability of clinical samples, either from primary or metastatic tumors." (PMID 41486114, 2026). "Moreover, macrophages exhibited a higher enrichment in paratumor samples compared to primary and metastatic tumor samples, in contrast to CD14 monocytes and granulocytes (left)." (PMID 38149248, 2023). "In addition, TAMs (CD206+CD45+CD11b+CD14+CD3−CD56−CD19−) infiltrated in primary tumors, paired omental metastatic tumors were compared, and the results confirmed the accumulation of CD206+ TAMs in the metastatic location." (PMID 39198883, 2024). "Thus, it is conceivable that the increase in intermediate (CD14++CD16+) monocytes is more actively triggered by the primary tumor, while tumor progression in metastatic disease results in a Th2-type cytokine milieu with counteracting effects." (PMID 22973451, 2012). "The highest frequency of CD14++CD16+ cell counts was, intriguingly, recorded for localized as opposed to metastatic disease which may reflect the preferential induction of intermediate monocytes in the early stages of cancer – a concept which was supported by in vitro studies." (PMID 22973451, 2012).
periodontal disease (7 papers, 2012 to 2022). "Clinical studies show that the local and systemic CD14 levels are substantially affected by periodontal disease." (PMID 27504628, 2016). "Finding compounds that trigger CD14 or toll-like receptors (TLRs) is potentially useful in periodontal disease." (PMID 26479870, 2015). "As shown in the boxplot, the expression of CD14, FCGR1A, DYNLL1, and FCGR2B correlated with disease status; therefore, these data suggest that these key genes may be important targets for the treatment of periodontal disease." (PMID 36212719, 2022).